MEGF10 (multiple EGF like domains 10)
Description:
Membrane receptor involved in phagocytosis by macrophages and astrocytes of apoptotic cells. Receptor for C1q, an eat-me signal, that binds phosphatidylserine expressed on the surface of apoptotic cells. Cooperates with ABCA1 within the process of engulfment. Promotes the formation of large intracellular vacuoles and may be responsible for the uptake of amyloid-beta peptides. Necessary for astrocyte-dependent apoptotic neuron clearance in the developing cerebellum. Plays role in muscle cell proliferation, adhesion and motility. Is also an essential factor in the regulation of myogenesis. Controls the balance between skeletal muscle satellite cells proliferation and differentiation through regulation of the notch signaling pathway (PubMed:28498977, Ref.16). May also function in the mosaic spacing of specific neuron subtypes in the retina through homotypic retinal neuron repulsion. Mosaics provide a mechanism to distribute each cell type evenly across the retina, ensuring that all parts of the visual field have access to a full set of processing elements.
Synonyms: KIAA1780; SR-F3; CMYO10A; CMYO10B; CMYP10A; CMYP10B; EMARDD
Tractability: Antibody: UniProt places it where antibodies can reach, with high confidence; its Gene Ontology location is reachable by antibodies, with high confidence; UniProt predicts a signal peptide or a membrane-spanning region; the Human Protein Atlas places it where antibodies can reach. PROTAC: UniProt records ubiquitination sites on it; ubiquitination databases record sites on it.
Gene: Protein-coding gene on chromosome 5 (127,290,796 to 127,465,737, forward strand). Ensembl gene ENSG00000145794.
Subcellular location: Cell membrane; Cell projection, phagocytic cup
Subcellular location (Human Protein Atlas): Plasma membrane
Gene Ontology:
Molecular function: complement component C1q complex binding; Notch binding; scavenger receptor activity
Biological process: homotypic cell-cell adhesion; muscle cell development; muscle cell proliferation; myoblast migration; positive regulation of cell-cell adhesion; positive regulation of myoblast proliferation; regulation of muscle cell differentiation; regulation of skeletal muscle tissue development; skeletal muscle satellite cell differentiation; apoptotic process involved in development; engulfment of apoptotic cell; skeletal muscle satellite cell activation; skeletal muscle satellite cell proliferation; cell development; myoblast development; vesicle-mediated transport
Cellular component: phagocytic cup; plasma membrane
Genetic constraint (gnomAD): Loss-of-function variants: 73 observed, 125.49 expected, observed/expected ratio (o/e) 0.58, 90% interval 0.48 to 0.71. The upper end of that interval is the gene's LOEUF score, 0.71, which puts it in group 2 of 6, group 1 being the genes least tolerant of losing a copy. Missense variants: 1,190 observed, 1,404.1 expected, observed/expected ratio (o/e) 0.85, 90% interval 0.81 to 0.89. Synonymous variants: 434 observed, 499.51 expected, observed/expected ratio (o/e) 0.87, 90% interval 0.8 to 0.94.
Gene-disease validity (ClinGen):
ClinGen rates the evidence that MEGF10 causes each of these diseases.
MEGF10-related myopathy (autosomal recessive): Definitive.
Homologues: Orthologues: chimpanzee MEGF10 (99% identical), macaque MEGF10 (99% identical), dog MEGF10 (95% identical), mouse Megf10 (95% identical), rabbit MEGF10 (94% identical), rat Megf10 (94% identical), guinea pig MEGF10 (94% identical), pig MEGF10 (92% identical), tropical clawed frog megf10 (82% identical), zebrafish megf10 (72% identical). Paralogues in human: MEGF11 (61% identical), MEGF6 (33% identical), GAS6 (11% identical).
Diseases named in the same sentence as MEGF10 in open-access papers:
MEGF10 is named in the same sentence as 40 diseases in open-access papers, as found by Europe PMC text mining. Sharing a sentence is not in itself a finding about the gene and the disease. The quoted sentences say what the papers report.
Areflexia (9 papers, 2017 to 2022). Absence of neurologic reflexes such as the knee-jerk reaction. "Biallelic loss‐of‐function MEGF10 mutations lead to MEGF10 myopathy, also known as early onset myopathy with areflexia, respiratory distress, and dysphagia (EMARDD)." (PMID 33159715, 2021). "Interestingly, recessive mutations in the MEGF10 gene have been reported to be associated with a rare disease called early‐onset myopathy–areflexia–respiratory distress–dysphagia syndrome (EMARDD)." (PMID 34328698, 2021). "Biallelic loss‐of‐function mutations in the encoding gene MEGF10 cause a recessive congenital muscle disease called MEGF10 myopathy; the classic form of this disease is also known as early onset myopathy with areflexia, respiratory distress, and dysphagia (EMARDD)." (PMID 33159715, 2021).
Stroke (6 papers, 2021 to 2024). Sudden impairment of blood flow to a part of the brain due to occlusion or rupture of an artery to the brain. "In response to stroke, reactive astrocytes engulf synapses through MEGF10, MERTK and GULP1-related pathways." (PMID 39086680, 2023). "We found that compared with the corresponding sham group, 14 days after stroke, MEGF10 and MERTK expression was significantly increased." (PMID 34836962, 2021). "Moreover, during the subacute post‐stroke stage, astrogliosis actively engulfs synapses via the Megf10 and Mertk pathways, and the inhibition of astrocyte‐related engulfment of synapses improves neurobehavioral outcomes in patients with ischemic stroke." (PMID 37081759, 2023). "A recent study revealed that MEGF10 and MERTK were expressed on the membranes of microglia/macrophages and astrocytes in mice with ischemic and hemorrhagic stroke and that MEGF10 and MERTK levels were significantly increased 14 days after stroke." (PMID 38727249, 2024). "Inducible ablation of astrocytic MEGF10 or MERTK reduces synaptic engulfment in the peri-infarct region and increases the number of dendritic spines 14 days after stroke, which also promotes enhanced functional recovery." (PMID 39086680, 2023). "MEGF10 and MERTK protein level was notably increased at 14 day following stroke." (PMID 34836962, 2021). "We found that Mac-2 was upregulated as early as 1 day following stroke, but without changes of MEGF10 and MERTK protein levels." (PMID 34836962, 2021). "For instance, M1-MG may exhibit excessive phagocytosis, also called phagoptosis, eliminating viable neurons and live synapses through multiple epidermal growth factor-like domains protein 10 (MEGF10) and tyrosine-protein kinase Mer (MERTK) in the post-stroke repair and remodeling stage." (PMID 35518646, 2022). "To determine whether MEGF10 and MERTK pathways mediate synapse engulfment after stroke, we investigated the expression and localization of MEGF10 and MERTK at different time points after stroke." (PMID 34836962, 2021). "By analyzing TUNEL+ apoptotic cells, we found that a lack of MEGF10 and MERTK did not affect cell death after stroke." (PMID 34836962, 2021). "We did not detect any abnormal behavior of mice that lacked MEGF10 or MERTK, at least within 14 days after stroke, suggesting the different mechanisms of de novo synapse formation in the developing brain and synapse remodeling after injury." (PMID 34836962, 2021).
ischemic stroke (4 papers, 2021 to 2024). A stroke disorder caused by obstruction of blood flow to the brain, due to thrombotic (local blood clot formation) or embolic (due to a blood clot or other material traveling from another site) event. "Here, the authors show in a murine model of ischemic stroke that inhibition of phagocytosis by MEGF10 and MERTK deletion in microglia and astrocytes attenuated damage and improved neurological outcomes by preventing synapse loss." (PMID 34836962, 2021). "By specifically deleting MEGF10 and MERTK phagocytic receptors, we determined that inhibiting phagocytosis of microglia/macrophages or astrocytes in ischemic stroke improved neurobehavioral outcomes and attenuated brain damage." (PMID 34836962, 2021). "MEGF10 and MERTK were also detected in astrocytes of mice after ischemic stroke and hemorrhagic stroke." (PMID 34836962, 2021). "To investigate the effects of MEGF10 and MERTK on dendritic spine structure after ischemic stroke, we performed Golgi-Cox staining to visualize neuronal dendritic spines in MEGF10WT, MERTKWT, C-MEGF10KO, C-MERTKKO, A-MEGF10KO, and A-MERTKKO mice." (PMID 34836962, 2021).
muscular dystrophy (4 papers, 2012 to 2022). Muscular dystrophy (MD) refers to a group of more than 30 genetic diseases characterized by progressive weakness and degeneration of the skeletal muscles that control movement. "For patient 2, comprehensive muscular dystrophy and myopathy gene panel revealed a splicing variant in MEGF10 (NM_032446.2:c.2980+5G>C:Exon21:Chr5:126784919)." (PMID 34828389, 2021). "This suggests that the molecular mechanism of the muscular dystrophy caused by JAG2 mutations overlaps with that underlying EMARDD, and also argues for JAG2 as a putative gene modifier in MEGF10-myopathy." (PMID 34740639, 2022). "Of these 30 GOSC genes selected on the basis of involvement in satellite cell biology, only 4 are also included in the 116 myopathogenes, so known to cause muscular dystrophies/myopathies when mutated: these are PAX7, MEGF10, SELENON (formerly SEPN1) and CAPN3." (PMID 34740639, 2022). "Thus, MEGF10 bears further investigation as a therapeutic target, not only for MEGF10 deficiency itself, but also for other inherited muscle diseases, including various forms of muscular dystrophy." (PMID 33159715, 2021).
congenital myopathy (3 papers, 2012 to 2021). "This study reports two unrelated Saudi patients with mild and severe congenital myopathy due to two different novel variants in MEGF10." (PMID 34828389, 2021). "Of seven patients in four reported families with congenital myopathy and mutations in MEGF10, one patient had cleft palate and an additional three patients had high-arched palate." (PMID 22371254, 2012). "Nonsense and frameshift mutations in MEGF10 were recently determined to be the cause of a severe congenital myopathy with diaphragmatic weakness, areflexia, and dysphagia." (PMID 22371254, 2012). "This explains satellite cells’ depletion in MEGF10 associated congenital myopathies." (PMID 34828389, 2021). "Similarly, patient WES31 and WES67 had adult onset disease due to mutations in genes typically associated with congenital myopathies (MEGF10 and MTM1 respectively)." (PMID 28877744, 2017). "Similarly one patient with adult onset symptoms had compound heterozygous mutations in a congenital myopathy gene, MEGF10 (WES36), who would not have been diagnosed by phenotype driven testing as diagnosis in this individual expands the phenotype associated with mutations in this gene." (PMID 28877744, 2017).
glioma (3 papers, 2017 to 2021). A benign or malignant brain and spinal cord tumor that arises from glial cells (astrocytes, oligodendrocytes, ependymal cells). "Moreover, gene ontology analysis demonstrated that MEGF10 was associated with cell migration, cell proliferation, and regulation of apoptosis in glioma." (PMID 29887919, 2018). "In a word, our results suggested that methylation level and mRNA expression of MEGF10 in glioma were not only correlated with IDH mutation but also associated with clinical outcome of patients, providing potential guide for future dissection of IDH role in glioma." (PMID 29887919, 2018). "To confirm MEGF10 as an independent predictor with previous widely accepted factors (age, WHO histological grade, and MGMT promoter status), we collected and analyzed the corresponding clinical and molecular information of glioma patients from TCGA datasets." (PMID 29887919, 2018).
hemorrhagic stroke (3 papers, 2021 to 2024). A stroke caused by a bleed on the brain. "Our immunostaining and in situ hybridization results demonstrated that MEGF10 and MERTK were upregulated in both reactive microgliosis and astrogliosis after ischemic or hemorrhagic stroke." (PMID 34836962, 2021). "Conditional knockout of MEGF10 or MERTK in microglia/macrophages attenuated the phagocytosis of synapses, which was shown to be helpful for improving dendritic spine structure and neurological dysfunction in an ischemic and hemorrhagic stroke mouse model." (PMID 38727249, 2024). "However, specific MEGF10KO and MERTKKO in astrocytes did not affect the number of spines, suggesting that microglia/macrophages but not astrocytes played a critical role in engulfing dendritic spines via MEGF10 and MERTK after hemorrhagic stroke." (PMID 34836962, 2021). "In this study, we revealed that at the poststroke repair and remodeling stage, reactive microgliosis and astrogliosis were active in engulfing synapses through MEGF10- and MERTK-related pathways, but showed different temporal phagocytic features in ischemic and hemorrhagic stroke." (PMID 34836962, 2021).
schizophrenia (3 papers, 2009 to 2021). A major psychotic disorder characterized by abnormalities in the perception or expression of reality. "In a recent study, we reported the association of MEGF10 with schizophrenia in our Irish family and case-control samples." (PMID 19721717, 2009). "MEGF10 and MERTK, which both have been linked to schizophrenia in association studies, encode phagocytic receptors trigger phagocytosis of target debris upon phosphatidylserine recognition." (PMID 33670154, 2021). "Blood brain barrier, brain damage, edema, and headache pathway effects, as well as a potential schizophrenia nodes with connections to MEGF10 and MEGF11 which binds Atrophin 1 (ATN1) a seizure related protein also appear." (PMID 32823271, 2020). "This study follows the same strategy and extends our finding of MEGF10 involvement in schizophrenia." (PMID 19721717, 2009). "Based on our study of the MEGF10 gene and its function in apoptosis, we hypothesize that the apoptotic engulfment pathways are involved in the etiology of schizophrenia." (PMID 19721717, 2009).
autism (2 papers, 2017 to 2023). Persistent deficits in social interaction and communication and interaction as well as a markedly restricted repertoire of activity and interest as well as repetitive patterns of behavior. "This evidence suggests that disrupted transcriptional regulation of MEGF10 contributes to autism risk." (PMID 28536440, 2017). "In summary, our findings suggest that MEGF10, which mediates axon pruning and synapse elimination during brain development, is associated with autism in the Chinese Han population." (PMID 28536440, 2017). "Based on the putative regulatory function of these common and rare variants in the TSS proximal region of MEGF10, these variants would seem to increase autism risk through reducing MEGF10 dosage." (PMID 28536440, 2017). "To investigate the role of MEGF10 variants with putative transcription regulatory function in the etiology of autism, we performed a family-based association study in 410 Chinese Han trios." (PMID 28536440, 2017). "Interestingly, SNPs in the transcription regulatory region of MEGF10 have been associated with increased risk of autism in a Chinese Han cohort, and MEGF10 expression was lower in peripheral blood of autistic individuals compared to healthy controls." (PMID 37415206, 2023). "We studied the genetic association of five SNPs in MEGF10 with autism in a Chinese Han cohort." (PMID 28536440, 2017). "In addition, the haplotype T-A-G composed of rs4836316, rs2194079 and rs4836317 that near the TSS seems to affect autism risk by modulating the transcriptional activity of MEGF10." (PMID 28536440, 2017). "On collectively considering both the role of MEGF10 and its regulation of synaptic pruning and the relationship of regulatory functional variants with disease, we hypothesized that variants in MEGF10 with putative transcriptional regulatory function might play a role in the pathogenesis of autism." (PMID 28536440, 2017). "In this study, we established a genetic relationship between MEGF10 and autism in the Chinese Han population." (PMID 28536440, 2017). "Furthermore, functional studies of MEGF10 in mice are required to illustrate its relationship with autism." (PMID 28536440, 2017). "Therefore, a critical role in the regulation of synaptic number and function suggests that MEGF10 is a candidate gene ﻿for autism." (PMID 28536440, 2017). "Therefore, the dampened MEGF10 expression may trigger synaptic dysregulation and disrupt the rate of synapse formation and pruning, thus playing a role in the pathogenesis of autism." (PMID 28536440, 2017).
Cognitive impairment (2 papers, 2025). Abnormal cognition is characterized by deficits in thinking, reasoning, or remembering. "Moreover, we showed that astrocytic Megf10 expression correlated with dysfunctional daily life activities, BPSD, and cognitive impairment, and astrocytes are involved in synapse pruning and clearance of neuronal debris through the MEGF10/MERTK signaling pathway." (PMID 41199342, 2025).
glioblastoma (2 papers, 2017 to 2020). The most malignant astrocytic tumor (WHO grade IV). "In addition to changes in Mmps, we also found that glioblastoma was associated with an increased expression of mRNAs encoding microglial phagocytic receptors—Cd93, Msr1, Cd36, Olr1, Megf10, Clec7a, and Scarf1." (PMID 32299465, 2020).